DNAJA4 (DnaJ heat shock protein family (Hsp40) member A4)
Synonyms: PRO1472; MST104; MSTP104
Tractability: Antibody: the Human Protein Atlas places it where antibodies can reach. PROTAC: ubiquitination databases record sites on it; its protein half-life has been measured.
Gene: Protein-coding gene on chromosome 15 (78,264,086 to 78,282,196, forward strand). Ensembl gene ENSG00000140403.
Subcellular location: Membrane
Subcellular location (Human Protein Atlas): Cytosol; Plasma membrane; Basal body; Centriolar satellite; Nuclear membrane; Primary cilium
Pathways (Reactome):
Cellular responses to stimuli: HSP90 chaperone cycle for steroid hormone receptors (SHR) in the presence of ligand
Gene Ontology:
Molecular function: protein binding; protein-folding chaperone binding; ATPase activator activity; ATP binding; heat shock protein binding; Hsp70 protein binding
Biological process: negative regulation of endothelial cell migration; negative regulation of inclusion body assembly; positive regulation of gene expression; protein refolding; cellular response to heat; protein folding; response to heat
Cellular component: cytosol; membrane
Genetic constraint (gnomAD): Loss-of-function variants: 28 observed, 37.49 expected, observed/expected ratio (o/e) 0.75, 90% interval 0.55 to 1.02. The upper end of that interval is the gene's LOEUF score, 1.02, which puts it in group 4 of 6, group 1 being the genes least tolerant of losing a copy. Missense variants: 406 observed, 489.44 expected, observed/expected ratio (o/e) 0.83, 90% interval 0.76 to 0.9. Synonymous variants: 171 observed, 178.41 expected, observed/expected ratio (o/e) 0.96, 90% interval 0.85 to 1.09.
Homologues: Orthologues: chimpanzee DNAJA4 (99% identical), macaque DNAJA4 (98% identical), dog DNAJA4 (97% identical), pig DNAJA4 (96% identical), rat Dnaja4 (94% identical), mouse Dnaja4 (93% identical), guinea pig DNAJA4 (88% identical), tropical clawed frog dnaja4 (73% identical), rabbit DNAJA4 (68% identical), zebrafish dnaja (59% identical). Paralogues in human: DNAJA1 (74% identical), DNAJA2 (56% identical), DNAJA3 (28% identical).
Diseases named in the same sentence as DNAJA4 in open-access papers:
DNAJA4 is named in the same sentence as 20 diseases in open-access papers, as found by Europe PMC text mining. Sharing a sentence is not in itself a finding about the gene and the disease. The quoted sentences say what the papers report.
melanoma (5 papers, 2019 to 2022). A malignant, usually aggressive tumor composed of atypical, neoplastic melanocytes. "DNAJA4 (DnaJ Heat Shock Protein Family (Hsp40) Member A4) encodes a heat shock protein previously shown to be involved in melanoma metastasis and angiogenesis regulation, but is generally poorly characterised." (PMID 33830993, 2021). "In melanoma, miR-1908-5p can target DNAJA4 and ApoE to promote the invasion and metastasis of MeWo-LM2 cells." (PMID 35463352, 2022). "miR-1908-5p targets APOE and DNAJA4 and promotes the invasion and metastasis of melanoma cells (MeWo-LM2)." (PMID 35463352, 2022). "DNAJA4 has been shown to promote metastasis and angiogenesis in melanoma, but may act as a tumour suppressor in stomach cancer." (PMID 30578123, 2019). "Among them, DNAJA4 can positively regulate ApoE, and extracellular ApoE can target the LRP1 receptor of melanoma cells and the LRP8 receptor of endothelial cells, thereby inhibiting cancer cell invasion, metastasis, colonization, and endothelial recruitment." (PMID 35463352, 2022). "The LRP1 ligand ApoE is targeted by miR-199a-3p and -5p, and miR-1908 and the heat shock factor DNAJA4, suppressing LRP1 signaling on melanoma and LRP8 on endothelial cells." (PMID 36612285, 2022).
nasopharyngeal carcinoma (3 papers, 2023 to 2025). A carcinoma arising from the nasopharyngeal epithelium. "For example, in nasopharyngeal carcinoma, DNAJA4 directly interacts with MYH9, recruiting PSMD2 to promote MYH9 ubiquitination and degradation, thereby inhibiting nasopharyngeal carcinoma migration and EMT." (PMID 39988672, 2025). "Moreover, it has been shown that DNAJA4 inhibits invasion and metastasis of nasopharyngeal carcinoma through PSMD2-mediated proteasomal degradation of MYH9." (PMID 39550407, 2024).
diabetes (2 papers, 2020 to 2025). "In addition, we identified nine genes (CABIN1, CKS1B, C19orf60, SDR39U1, SLC31A1, DNAJA4, ZC3H8, OTUD3 and UBALD1) not previously associated with diabetes, but that are known to be involved in processes potentially linked to β-cell dysfunction, such as cell turnover, oxidative stress and ER stress." (PMID 33575641, 2020).
alveolar rhabdomyosarcoma (1 paper, 2023). A rapidly growing malignant mesenchymal neoplasm. "Promoter hypermethylation of DNAJA4 has also been reported in several other diseases, such as paediatric embryonal and alveolar rhabdomyosarcomas, Ewing sarcoma, and oral leukoplakia." (PMID 37875476, 2023).
chronic hepatitis B (1 paper, 2025). "In chronic hepatitis B (CHB) patients, immune active phase (IA) is associated with higher intrahepatic expression of MSX1, DNAJA4 and CRYAB, and lower serum HBV markers compared to immune tolerant (IT) phase." (PMID 39883729, 2025).
colon cancer (1 paper, 2020). "For instance, DNAJA4 has been shown in human colon cancer cells to be regulated by SREBP and act as a mediator of lipotoxicity through ER stress." (PMID 33575641, 2020).
COVID-19 (1 paper, 2025). A disease caused by infection with severe acute respiratory syndrome coronavirus 2. "Our analysis revealed increased plasma levels of DNAJC9, DNAJC17, and DNAJA4 in PLWH diagnosed with COVID-19, though these elevations were not statistically significant after FDR adjustment." (PMID 40568587, 2025).
HIV-1 infection (1 paper, 2021). The type species of lentivirus and the etiologic agent of acquired immunodeficiency syndrome (AIDS). "The heat shock protein (HSP) family member DNAJA4 is induced in T-cells in heat shock and in HIV-1 infection." (PMID 34885095, 2021).
stomach adenocarcinoma (1 paper, 2019). "DNAJA4 and its methylation status may be a new biomarker for stomach adenocarcinoma, although this may not be applicable to other carcinomas." (PMID 30578123, 2019). "We observed a strong negative correlation between DNAJA4 gene methylation and expression in stomach adenocarcinoma, which suggested that methylation of DNAJA4 may suppress gene expression." (PMID 30578123, 2019).
virus infection (1 paper, 2022). "The expression and localization of EPC DNAJA4 before and after virus infection, its effect on CGSIV replication, and its interaction with CGSIV replication-related proteins were investigated." (PMID 36672799, 2022). "Immunofluorescence was used to further investigate the localization of EPC DNAJA4 after virus infection." (PMID 36672799, 2022). "Our results demonstrate for the first time that EPC DNAJA4 is involved in viral infection by promoting viral DNA replication and interacting with proteins associated with viral replication." (PMID 36672799, 2022). "All of these studies highlight the importance of DNAJA4 in viral infections, and DNAJA4 has the potential to become an emerging therapeutic target in the field of viral research." (PMID 36672799, 2022). "Studies have shown that DNAJA4 is widely involved in several virus infections." (PMID 36672799, 2022). "The results suggest that EPC DNAJA4 may play a role in the packaging and assembly of virions in the later stage of virus infection and promote the replication of CGSIV DNA by promoting the replication of CGSIV DNA." (PMID 36672799, 2022). "Within 0–48 h of viral infection, the transcript level of DNAJA4 increased with the extension of viral infection time compared with that of the mock group (inactivated CGSIV), and the peak value was 3.75 times that of the mock group, with a statistically significant difference (p < 0.0001)." (PMID 36672799, 2022). "In addition, studies have shown that DNAJA4 also plays a crucial role in viral infections." (PMID 36672799, 2022). "The results indicated that the localization of EPC DNAJA4 changed after virus infection, and some EPC DNAJA4 entered the nucleus from the cytoplasm." (PMID 36672799, 2022). "It is speculated that DNAJA4 may be involved in the transfer of the CGSIV virus from the nucleus to the cytoplasm, thereby promoting DNA replication in the later stages of virus infection." (PMID 36672799, 2022). "Further study of viral DNA copy number showed that overexpression of EPC DNAJA4 did not promote CGSIV DNA replication in the early stage of viral infection (0–6 h) but promoted CGSIV DNA replication at 16 h of viral infection." (PMID 36672799, 2022).
tumor (10 papers, 2013 to 2025). "Conversely, the genes FTH1, SQSTM1, HSPA6, TSPYL2, PHLDA2, ITGAX, and DNAJA4 are expected to act as versatile protein regulators, potentially suppressing tumor cell genetic instability and promoting autophagy, apoptosis, and other forms of cell death." (PMID 40986633, 2025). "H&E staining of the foot pad tumours demonstrated that the tumours in the DNAJA4-overexpression group exhibited less aggressive behaviour, characterized by intrusive invasions into the skin or muscle, than those in the Ctrl group." (PMID 37875476, 2023). "In summary, these results demonstrate that low expression of DNAJA4 indicates a poor prognosis and is correlated with tumour metastasis in NPC patients." (PMID 37875476, 2023). "Increased expression of DNAJA4 has been shown to suppress tumor invasion." (PMID 27330572, 2016). "The results of IHC assay revealed that MYH9 was downregulated in DNAJA4-overexpressing tumours, while PSMD2 expression had no obvious change." (PMID 37875476, 2023). "When comparing our gene expression analyses and genetic analyses, the cancer genes HLA-DPA1, HLA-DMB, DNAJA4, LY86, HCLS1, GABBR1, NUDT16 showed upregulation in tumor tissue compared to cell subpopulations and are located in chromosomal regions that showed losses in GSC and CD133pos./CD15pos. cells." (PMID 32634135, 2020).
cancer (7 papers, 2013 to 2025). A tumor composed of atypical neoplastic, often pleomorphic cells that invade other tissues. "Among the target genes of miR-1908-5p, PTEN, DNAJA4, ApoE, and HDAC10 were associated with cancer cell invasion and metastasis." (PMID 35463352, 2022). "Interestingly, cross‐sectional studies showed that plasma levels of DNAJA4 increased with various types of cancers." (PMID 40211681, 2025). "We have extended our investigation by evaluating the role of all human DNAJAs (DNAJA1, DNAJA2, DNAJA3, and DNAJA4) in the response of cells to cancer therapeutic agents, such as doxorubicin, cisplatin, and etoposide, and to define cytotoxic stresses such as ROS and heat shock." (PMID 32149145, 2020).
infection (2 papers, 2014 to 2020). The state of being infected such as from the introduction of a foreign agent such as serum, vaccine, antigenic substance or organism. "In contrast, Dnaja4, Dnajb1a, Dnajc5aa, Dnajc6, and Dnajc16L were up-regulated in at least two time points after infection, suggesting their up-regulated expression was more lasting." (PMID 25542027, 2014). "However, in the liver, and Dnaja4 and Dnajc3 were down-regulated more than five-fold in the liver after infection with ESC." (PMID 25542027, 2014). "Moreover, genes involved in active metabolism like COX7A2, NDUFB6 (ILC2), NDUFA12 (ILCP), ACSL1 (NK CD16high), and DNAJA4 (NK CD56high) were upregulated in HIV-infected children, suggesting active metabolism in these subsets in response to infection." (PMID 32937142, 2020).
bacterial infection (1 paper, 2018). "Furthermore, DNAJA4 is induced in the course of an unfolded protein response in Atlantic salmon and early after bacterial infection in channel catfish Ictalurus punctatus." (PMID 30073015, 2018).
DNAJA4 also shares sentences with these, for which no sentence is quoted: breast carcinoma (1 paper); Ewing sarcoma (1); heart failure (1); Oral leukoplakia (1); sarcoma (1); stomach cancer (1).